FN1 (fibronectin 1)
Diseases named in the same sentence as FN1 in open-access papers (continued):
Sharing a sentence is not in itself a finding about the gene and the disease.
melanoma (continued). "Interestingly, the genes coordinately expressed with CTHRC1, i.e. ITGB3, NFAT, and FN1, have all been implicated in angiogenesis, suggesting that these molecules may be associated with the increased angiogenesis and blood vessel density detected in melanomas." (PMID 26918341, 2016). "Noteworthy, the elevated level of mRNA expression of fibronectin 1 was found in T+ and T++ melanoma cells, while laminin α3 was detected only in T-cadherin expressing cells, suggesting their important role in the increased invasive potential of these cells." (PMID 26197340, 2015). "Here, we showed that the secretome of senescent melanoma cells drives basal melanoma cells towards a mesenchymal phenotype, with characteristic of stems illustrated by increased level of the prototype genes FN1, SNAIL, OCT4 and NANOG." (PMID 24344100, 2013). "We observed that RNA expression of the β-catenin target genes fibronectin (FN1) and axin (Axn2) were upregulated in primary melanomas and melanoma metastases compared to benign nevi." (PMID 21858114, 2011). "In addition, the involvement of CSPG4 in the adhesion and motility of melanoma cells on FN1 substrates has been reported." (PMID 38338902, 2024). "Transcriptome sequencing of EGR3‐expressing A375 melanoma cells revealed significant up‐regulation of multiple genes associated with the extracellular matrix (ECM), such as COL1A1, COL5A3, and FN1, thereby confirming the regulatory role of EGR3 in the remodeling of the extracellular space." (PMID 38973154, 2024). "FN1-high melanoma cells were found to reside in hypoxic environments suggesting that there exists an interplay between environmental cues and the aggressiveness of melanoma cells." (PMID 35186184, 2022). "Indeed, RNA-sequencing data indicated that A375 human melanoma cells express high levels of fibronectin (FN1) and several laminin genes." (PMID 36229674, 2022). "Additionally, treatment with statins reduces melanoma cell adhesion to FN1 as well as to other matrix components, including collagens and laminin, in parallel to reduction of lung metastasis and cell invasion." (PMID 33731188, 2021). "We and others have shown that blocking drivers of relevant heterogeneous phenotypes can improve the outcome of targeted therapy in melanoma, and our data presented here suggest that blocking FN1‐mediated interactions can interfere with melanoma at various stages of disease progression." (PMID 32145051, 2020). "Another interesting finding in our analyses was the potential role of FN1 (fibronectin 1) in melanoma and a candidate mechanism by which the combination of vemurafenib and tretinoin may mediate its effects." (PMID 30820351, 2019). "Interestingly, we found that CTHRC1 and FN1 mRNA expression correlated in primary melanocytes, nevus cells, and melanoma cells, as well as in melanoma cell lines and primary melanoma tissues." (PMID 26918341, 2016). "Furthermore, we have previously demonstrated that the EDA-containing FN1 (cFN) is upregulated in forming or newly formed blood vessels in melanoma lymph node metastases." (PMID 26918341, 2016). "FN1 is known to play a role during tumor immune evasion by regulating extracellular matrix (ECM) remodeling.Finally, when comparing ASEs detected in melanoma versus 19 normal tissues from ENCODE, we found that cancer cells contained 787 atypical ASEs (Fisher’s exact test, P = 4.748e-20)." (PMID 41273175, 2025). "Thus, elevated levels of FN1 may induce the coordinate expression of CTHRC1 in melanoma cells by activating the αvβ3 integrin receptor." (PMID 26918341, 2016). "Interestingly, we found several genes involved in the ECM modification, such as FN1 and P4HA1, which may be expressed by both melanoma and stromal cells, to be associated with metastasis and patient prognosis." (PMID 26918341, 2016).
melanoma (continued). "The LAMININ, FN1, ADGRE5, SPP1, MK, CDH1, and APP signals mainly originated from melanoma cells and were received by multiple cell types, suggesting that melanoma cells play extensive roles in the ecosystem." (PMID 41357561, 2025). "In some metastatic melanoma samples, we also observed a subset of CD163+ TAMs in melanoma tumours co-localised with DPP4, FN1, and COX2 proteins." (PMID 38903497, 2024). "We found that YY1-knockdown melanoma cells were more sensitive to TGF-β1 stimulation, in that YY1 knockdown cells treated with TGF-β1, boosted the expression of the EMT genes FN1, CDH2, ZEB1, SNAI1 and VIM, among others." (PMID 35693944, 2022). "Extensive studies investigating Fn1 have shown that it inhibits apoptosis and regulates EMT to promote melanoma proliferation and metastasis." (PMID 34539543, 2021). "Also, AMBRA1 expression negatively correlated with the expression of the mesenchymal genes CDH2, FN1 and VIM, whereas a positive correlation was evident for the epithelial marker CDH1, hence suggesting that an active EMT-like process is associated with low AMBRA1 expression in human melanoma cells." (PMID 33953176, 2021). "Using such tissue proteomics approaches, several potential biomarkers have been identified from melanoma, such as actin-related protein 2/3 complex, subunit 2 (ARPC2), fibronectin 1 (FN1), and regulator of G protein signaling 1 (RGS1)." (PMID 29039819, 2017). "At the protein level, FN1, ITGB3, and NFATC2 were expressed in a manner similar to CTHRC1 in our panel of melanoma cell lines." (PMID 26918341, 2016). "By comparing gene expression in the primary and wound metastatic lesion of the melanoma patient, we found that among genes related to wound healing, genes of ECM proteins, including POSTN, COL1A1, and FN1, were overexpressed in the wound metastatic lesion." (PMID 26083413, 2015). "Furthermore, WAY-316606 markedly impaired the migratory and invasive capacities of metastatic melanoma cells, accompanied by downregulation of key ECM remodeling and fibrosis-related genes, including VIM, CCN2, FN1, and TGFBI." (PMID 42279305, 2026). "Here we show that SALL4 can build a protein complex together with HDAC2 also in human melanoma cells and that SALL4 and HDAC2 together directly bind to genes involved in melanocyte and melanoma biology, such as VEGFR-1, CDH2 (N-cadherin), FN1, TGFBR2, MITF, and others." (PMID 34417458, 2021). "At the cellular level, there was no proliferative advantage when 501mel cells were co‐cultured with WM266‐4 cells, but there was a significant effect on survival in heterogeneous melanoma spheres and this effect was dependent on the ability of WM266‐4 cells to express FN1." (PMID 32145051, 2020). "On the basis of overlapping marker genes and proteins (for example, FN1 upregulation and MITF downregulation), we identified a biological similarity to a reported phenotypic switch in (BRAF inhibitor-naive) melanoma, as reported in a series of publications by Hoek, Dummer and colleagues." (PMID 27648299, 2016). "Whereas the role of TNC (tenascin C) and FN1 (fibronectin 1) in melanoma development is well documented, implication of MARCKS, RCN3, BAMBI, PEA3/ETV4 and the FK506 family members FKBP7, FKBP10 and FKBP11 in melanoma progression is unclear." (PMID 27689402, 2016). "The gain of invasive capability was also associated with an increased expression of EMT genes (e.g., CDH2, FN1, VIM, SNAI1), as revealed by both RT-qPCR and WB analyses of bulk tumors, Bdmc+/+ and Bdmc−/− cells and siAMBRA1 human melanoma SK-Mel-5, MeWo and SK-Mel-2 cells." (PMID 33953176, 2021). "However, LEF1 is presumably not the only mediator of FN1 expression, as FN1 is also expressed in cells lacking LEF1, for instance melanoma-derived MV3 cells." (PMID 23677615, 2013).
liver fibrosis (66 papers, 2013 to 2026). "Astonishingly, these findings are in line with seminal reports demonstrating that CXCL1, CXCL11, HIF1A, COL4A1, and FN1 are implicated in liver fibrosis." (PMID 32161843, 2020). "This study also looked at FN1, a gene playing a crucial role in liver fibrosis, as it is usually required for collagen matrix assembly and to support other matrix proteins." (PMID 38338770, 2024). "This induces the deactivation of CAFs, with the consequent reduction in the secretion of ECM components (COL1A1, COL1A2, and FN1) and liver fibrosis." (PMID 36443822, 2022). "Next, we measured the mRNA expression of genes involved in ECM accumulation and liver fibrosis like Fn1 and collagen type I (COL1A1, Col1a1)." (PMID 35087411, 2021). "The expression levels of several hepatic fibrosis markers such as alpha smooth muscle actin (αSMA), collagen type 1 alpha 1 chain (Col1A1), fibronectin 1 (FN1), PCNA and tissue inhibitor of metalloprotease 1 (TIMP1) were tested by RT-qPCR." (PMID 29125588, 2017). "For example, herein, HBV integration in FN1 occurred preferentially in patients with high liver fibrosis stage to in those with low fibrosis stage." (PMID 29212479, 2017). "Furthermore, the immunohistochemical staining results revealed that the distribution of the key marker of liver fibrosis, FN1 was significantly increased around hepatic portal areas in the BDL group, which was markedly reduced with SWT treatment." (PMID 39741334, 2024). "Moreover, FN1, COL1, and iNOS axis-mediated liver fibrosis were caused by DOX, and our data documented the fibrotic effect of DOX via the upregulation of VEGF, Wnt7b, β-catenin, FN1, Col-1, TGFβ1, iNos, and Bax in the DOX group." (PMID 37296647, 2023). "Mechanistically, FN1 expressed from iECs led to the upregulation of Itgα5/β1 and Hnf4α in iHEAs and were correlated to the decreased expression of genes related to hepatic stellate cell activation such as Lox and Spp1 in the cholestatic liver fibrosis animals." (PMID 35883684, 2022). "EV FN1 was dispensable for the interaction of EVs with cell surface heparin-like molecules, for EV uptake by clathrin- and caveolin-mediated endocytosis, and for EV-mediated therapy of CCl4-induced hepatic fibrosis in mice." (PMID 33816490, 2021). "Given that FN1 is a key modulator of fibrosis, the HBV-FN1 fusion protein may be involved in the pathogenesis of liver fibrosis." (PMID 29861854, 2018). "Thus, the expression of many hepatic fibrosis markers such as Col1A1, FN1, MMP9 and TIMP1 was more abundant in GWI-BDL group than in naïve-BDL controls." (PMID 30177688, 2018). "Furthermore, the mRNA and protein levels of hepatic markers that could be used to determine the degree of liver fibrosis, such as Acta2, Col1a1 and Fn1 were markedly elevated by CCl4 but inhibited by SWT in different doses." (PMID 34736501, 2021). "Given that FN1 is a key modulator of fibrosis, the HBV-FN1 fusion protein is possibly involved in the pathogenesis of liver fibrosis." (PMID 34442866, 2021). "More importantly, introduction of miR-122 into CCl4-treated mice attenuated the expression of FN1 and SRF in fibrotic livers, and alleviate hepatic fibrosis in vivo." (PMID 25909171, 2015). "In contrast, aged mice exhibited hepatic fibrosis, with increased collagen deposition and upregulation of genes related to fibrosis (Acta2, MMP2, TGF-ß1, and Col1a2), cirrhosis (CXCR4, SOX9, DCN, and MFAP4), and cancer (Bcl2, CDKN2a, c-Myc, and Fn1)." (PMID 39851554, 2025). "Furthermore, we examined the relative mRNA expression levels of key markers related to hepatic fibrosis (Acta2, Cola2, TGF-β1, and MMP2), cirrhosis (CXCR4, SOX9, DCN, and MFAP4), and cancer (Bcl2, CDKN2a, c-Myc, and Fn1) across the experimental groups." (PMID 39851554, 2025).
liver fibrosis (continued). "Combined with our own data in liver fibrosis and studies in other organs, we were able to further scrutinize these data to identify a cohort of highly expressed ECM proteins amenable to assay in patient serum samples, including OPN, VIM, SPARC, GPNMB and FN1." (PMID 30559459, 2018). "During hepatic fibrosis, ECM is changed from a type IV collagen-rich composition to a type I collagen- and fibronectin 1 (FN1)-rich composition, which distorts the architecture of the liver, and leads to hepatic cirrhosis and consequently hepatocellular cancer (HCC)." (PMID 25909171, 2015). "All these data suggest that FN1 and SRF are bona fide targets of miR-122, and miR-122 may suppress hepatic fibrosis by simultaneously blocking multiple aspects of fibrogenesis, including collagen production, fibril assembly and ECM contraction." (PMID 25909171, 2015). "The observed discrepancy between mRNA and protein levels of Fn1 is not surprising: previously, a similar ratio of Fn1 (high mRNA and low protein levels) was observed in the acute phase of CCl4-induced liver injury in rats preceding liver fibrosis." (PMID 35625754, 2022). "Moreover, HBV integrations in the FN1 gene occur preferentially in cases with a high liver fibrosis stage rather than in cases with a low fibrosis stage." (PMID 34442866, 2021).
diabetes (63 papers, 2004 to 2026). "Diabetes increased kidney expression of genes associated with injury (Kim1, ten-fold), senescence (Cdkn1a, Cdkn2a, 10 to 18-fold) and fibrosis (Tgfb1, Ctgf, Pai1, Timp1, Col1α1, Col4α1 and Fn1, two- to six-fold)." (PMID 41332229, 2025). "Our hypothesis is that OPN and FN1 may contribute to the extracellular matrix remodeling in HFpEF that can be exacerbated through advanced glycation end products associated with diabetes." (PMID 33330671, 2020). "Diabetes causes FN1 upregulation in the retina, kidney, heart, and plasma." (PMID 27781209, 2016). "The interactions between periportal and pericentral hepatocytes, mediated by Fgf, Agt, Nectin1, Vtn, Sema4a, Angpt, Fn1, and Des, were lost in the livers of mice with diabetes at the late-stage." (PMID 39494341, 2024). "Gene expression of the myofibroblast marker α-smooth muscle actin (Acta2) and matrix molecules collagen 1 (Col1a1), collagen IV (Col4a3) and fibronectin (Fn1) were all increased 2- to 3- fold in kidneys at week 12 of diabetes." (PMID 38391050, 2024). "Diabetes wound healing is a dynamic process that overlaps proliferation, inflammation and coagulation, among which FN1 and MMP1 play a key role in wound healing." (PMID 37057206, 2023). "Fibrotic genes in the glomeruli were elevated by diabetes, including fibronectin (Fn1), TGFβ1 (Tgfb1), and collagen α-1 (IV) chain (Col4a), with significant attenuation in diabetic PPKM2Tg mice." (PMID 35133981, 2022). "The Fn1 gene and protein are upregulated by high glucose exposure or diabetes and in chronic wounds, as already described." (PMID 35386010, 2022). "There was diabetes-induced upregulation of Acta2 (an indicator of fibrosis), Fn1 (participates in extracellular matrix formation), and Col 4 (main component of the glomerular basement membrane) in renal tissues." (PMID 34149434, 2021). "FN1 was associated with two risk factors (CVD and diabetes) and one pathogenesis process (immune response)." (PMID 32466277, 2020). "Diabetes leads to the upregulation of FN1 via an endothelin- (ET-) dependent pathway involving activation of NF-κB and AP-1 transcription factors." (PMID 27781209, 2016). "The CELF2-related AS events of NECTIN2, DYRK1B, SF1 and FN1 were significantly different and may be potential therapeutic targets for diabetes-related vascular disease." (PMID 40692719, 2025). "In addition, diabetes-induced higher mRNA levels of Fibronectin-1, Collagen-1, and TGF-β were markedly inhibited with dapagliflozin, even though the gene expression of Collagen-1 was not changed in ZDF rats as compared with lean controls." (PMID 37386620, 2023). "Perhaps, the gain-of-function of the Lgals3bp–Itgb1 and Fn1–Itgb1 pairs may explain the role of Hrchi fibroblasts in diabetic myocardial fibrosis." (PMID 37010266, 2023). "The hub genes CEBPD, TP73, ESR2, TAB1, MAP 3K5, FN1, UBD, RUNX1, PIK3R2 and TNF, which might play an essential role in obesity associated type 2 diabetes mellitus was further screened." (PMID 33902539, 2021). "Also, endothelin- (ET-) dependent pathway is involved in the up-regulation of FN-1 during diabetes that involves activation of NF-kβ and AP1 transcription factors." (PMID 33304382, 2020). "Simultaneously, severe immune cell infiltration of Mpo and Cxcr2 along with elevated levels of Fn1 might have antagonized damage in the diabetic pancreas." (PMID 26110898, 2015). "Interestingly, diabetes-related alterations of the extracellular matrix and adhesion molecules were varied; Pecam, Mmp10, Lamc1, Itgb7, Mmp9, and Timp4 were up-regulated, but Col11a1, Fn1, Admts2, and Itgav were down-regulated." (PMID 21984919, 2011). "We further examined the expressions of several extracellular matrix(ECM) genes, COL1A1, COL4A1, and FN1, because the gene set enrichment analysis indicated enrichment of ECM deposition by MECs in diabetes." (PMID 39739865, 2024).
diabetes (continued). "Fibronectin 1 (FN1) is a member of the glycoprotein family, which is involved and functions as a biomarker in hypertension, diabetes, obesity, and lung cancer." (PMID 36685671, 2023). "FN1 and VTN, like other factors involved in the coagulation process, are known to increase not only in stroke patients but also in CVD and diabetes patients." (PMID 32466277, 2020). "The data showed that compared with the control group, the expression levels of CASP3, VCAM-1 and HGF were down-regulated in patients with syphilis and diabetes, while ALB, FN1, MMP9, IL8, CTGF, STAT3 and IGF1 were up-regulated." (PMID 32342229, 2020). "Chronic inflammation occurred in the diabetic pancreas accompanied by up-regulation of CCAAT/enhancer-binding protein beta (C/EBPβ) and its targets (TNFα, Il6, CRP, and Fn1) as well as myeloperoxidase (Mpo) and C-X-C chemokine receptor type 2 (Cxcr2)." (PMID 26110898, 2015). "The observed increases in COL4A1, FN1 and phosphorylation of both ERK1/2 and SMAD-2 were prevented when miR-133a was overexpressed in the heart in diabetes." (PMID 24428157, 2014). "In our current study, we show that p300 mRNA levels increase with diabetes and this increase was correlated with an increase in mRNA levels of fibrosis inducers: EDN1, AGT, CTGF and TGF-β1, and ECM genes, e.g. COL4A1 and FN1." (PMID 24428157, 2014). "Notably, the PI3K-Akt signaling pathway, a critical pathway in diabetes, was enriched with additional key targets, including IL6, HSP90AA1, FN1, MAPK1, AKT1, PIK3R1, and MAPK3." (PMID 40170727, 2025). "Through endothelial-specific expression of miR9, levels of COL1A1 and FN1 were both significantly reduced in diabetes and restored to baseline non-diabetic." (PMID 39042659, 2024). "In mice treated with empagliflozin, the diabetes-induced upregulation of Tgfβ1 and Cd14 was absent and there was a trend for reduced Fn1 expression compared to vehicle-treated db/db mice (P = 0.059)." (PMID 27226136, 2016). "Metformin did not restore the diabetes-induced upregulation of any genes but tended to decrease Fn1 (P = 0.095) and Tgfβ1 (P = 0.068) compared to db/db vehicle." (PMID 27226136, 2016).